NCOA6 (nuclear receptor coactivator 6)
Description:
Nuclear receptor coactivator that directly binds nuclear receptors and stimulates the transcriptional activities in a hormone-dependent fashion. Coactivates expression in an agonist- and AF2-dependent manner. Involved in the coactivation of different nuclear receptors, such as for steroids (GR and ERs), retinoids (RARs and RXRs), thyroid hormone (TRs), vitamin D3 (VDR) and prostanoids (PPARs). Probably functions as a general coactivator, rather than just a nuclear receptor coactivator. May also be involved in the coactivation of the NF-kappa-B pathway. May coactivate expression via a remodeling of chromatin and its interaction with histone acetyltransferase proteins.
Synonyms: PRIP; AIB3; KIAA0181; RAP250; TRBP; ASC2; NRC
Tractability: PROTAC: its protein half-life has been measured.
Gene: Protein-coding gene on chromosome 20 (34,689,097 to 34,825,739, reverse strand). Ensembl gene ENSG00000198646.
Subcellular location: Nucleus
Subcellular location (Human Protein Atlas): Nucleoplasm
Pathways (Reactome):
Circadian clock: BMAL1:CLOCK,NPAS2 activates circadian expression; Expression of BMAL (ARNTL), CLOCK, and NPAS2; RORA,B,C and NR1D1 (REV-ERBA) regulate gene expression
Gene expression (Transcription): Epigenetic regulation of gene expression by MLL3 and MLL4 complexes; Formation of WDR5-containing histone-modifying complexes; MLL4 and MLL3 complexes regulate expression of PPARG target genes in adipogenesis and hepatic steatosis
Metabolism: Activation of gene expression by SREBF (SREBP); PPARA activates gene expression; Regulation of lipid metabolism by PPARalpha
Cellular responses to stimuli: Cytoprotection by HMOX1; Heme signaling
Developmental Biology: Activation of anterior HOX genes in hindbrain development during early embryogenesis; Transcriptional regulation of white adipocyte differentiation
Organelle biogenesis and maintenance: Transcriptional activation of mitochondrial biogenesis
Gene Ontology:
Molecular function: enzyme binding; nuclear thyroid hormone receptor binding; protein binding; transcription coactivator activity; chromatin binding; nuclear estrogen receptor binding; nuclear retinoid X receptor binding
Biological process: DNA damage response; DNA-templated transcription initiation; myeloid cell differentiation; positive regulation of transcription by RNA polymerase II; brain development; heart development; positive regulation of DNA-templated transcription; response to hormone
Cellular component: histone methyltransferase complex; MLL3/4 complex; nucleoplasm; nucleus; transcription regulator complex
Genetic constraint (gnomAD): Loss-of-function variants: 48 observed, 169.88 expected, observed/expected ratio (o/e) 0.28, 90% interval 0.22 to 0.36. The upper end of that interval is the gene's LOEUF score, 0.36, which puts it in group 1 of 6, group 1 being the genes least tolerant of losing a copy. Missense variants: 2,214 observed, 2,642.2 expected, observed/expected ratio (o/e) 0.84, 90% interval 0.81 to 0.87. Synonymous variants: 894 observed, 961.95 expected, observed/expected ratio (o/e) 0.93, 90% interval 0.88 to 0.98.
Homologues: Orthologues: chimpanzee NCOA6 (99% identical), macaque NCOA6 (99% identical), dog NCOA6 (95% identical), rabbit NCOA6 (94% identical), guinea pig NCOA6 (93% identical), rat Ncoa6 (92% identical), mouse Ncoa6 (92% identical), tropical clawed frog ncoa6 (51% identical), zebrafish ncoa6 (41% identical).